NPC1 (NPC intracellular cholesterol transporter 1)
Description:
Intracellular cholesterol transporter which acts in concert with NPC2 and plays an important role in the egress of cholesterol from the endosomal/lysosomal compartment. Unesterified cholesterol that has been released from LDLs in the lumen of the late endosomes/lysosomes is transferred by NPC2 to the cholesterol-binding pocket in the N-terminal domain of NPC1. Cholesterol binds to NPC1 with the hydroxyl group buried in the binding pocket. Mediates cholesterol transfer from lysosomes to endoplasmic reticulum by tethering endosomal/lysosomal compartments and endoplasmic reticulum membrane contact sites where it interacts with sterol transport protein GRAMD1B. Binds oxysterol with higher affinity than cholesterol. May play a role in vesicular trafficking in glia, a process that may be crucial for maintaining the structural and functional integrity of nerve terminals (Probable). Inhibits cholesterol-mediated mTORC1 activation throught its interaction with SLC38A9. (Microbial infection) Acts as an endosomal entry receptor for ebolavirus.
Synonyms: SLC65A1; NPC; POGZ
Tractability: Small molecule: a structure with a bound ligand is known; a high-quality ligand is known; it has a binding pocket of medium quality; it belongs to a druggable protein family. Antibody: its Gene Ontology location is reachable by antibodies, with high confidence; UniProt predicts a signal peptide or a membrane-spanning region. PROTAC: ubiquitination databases record sites on it; its protein half-life has been measured; a small molecule that binds it is known.
Target class: Transporter
Chemical probes: U18666A
Gene: Protein-coding gene on chromosome 18 (23,506,184 to 23,586,969, reverse strand). Ensembl gene ENSG00000141458.
Subcellular location: Late endosome membrane; Lysosome membrane
Pathways (Reactome):
Transport of small molecules: LDL clearance
Gene Ontology:
Molecular function: cholesterol transfer activity; protein binding; cholesterol binding; signaling receptor activity; transmembrane signaling receptor activity; lipid transporter activity
Biological process: autophagy; cholesterol efflux; cholesterol homeostasis; cholesterol transport; establishment of protein localization to membrane; glycoprotein biosynthetic process; intracellular cholesterol transport; intracellular lipid transport; lysosome to ER cholesterol transport; membrane raft organization; negative regulation of TORC1 signaling; symbiont entry into host cell; bile acid metabolic process; intestinal cholesterol absorption; lysosomal transport; sterol transport; gene expression; negative regulation of epithelial cell apoptotic process; response to cadmium ion
Cellular component: cytoplasmic side of lysosomal membrane; endoplasmic reticulum; extracellular exosome; late endosome membrane; lysosomal membrane; membrane; nuclear envelope; perinuclear region of cytoplasm; plasma membrane; extracellular region; lysosome; endosome; Golgi apparatus; membrane raft; vesicle
Genetic constraint (gnomAD): Loss-of-function variants: 70 observed, 126.33 expected, observed/expected ratio (o/e) 0.55, 90% interval 0.46 to 0.68. The upper end of that interval is the gene's LOEUF score, 0.68, which puts it in group 2 of 6, group 1 being the genes least tolerant of losing a copy. Missense variants: 1,430 observed, 1,619.5 expected, observed/expected ratio (o/e) 0.88, 90% interval 0.85 to 0.92. Synonymous variants: 635 observed, 628.25 expected, observed/expected ratio (o/e) 1.01, 90% interval 0.95 to 1.08.
Gene-disease validity (ClinGen):
ClinGen rates the evidence that NPC1 causes each of these diseases.
Niemann-Pick disease, type C1 (autosomal recessive): Definitive. Type C Niemann-Pick disease associated with a mutation in the gene NPC1, encoding Niemann-Pick C1 protein.
Homologues: Orthologues: chimpanzee NPC1 (98% identical), macaque NPC1 (97% identical), rabbit NPC1 (90% identical), pig NPC1 (90% identical), dog NPC1 (89% identical), guinea pig NPC1 (88% identical), mouse Npc1 (86% identical), rat Npc1 (86% identical), tropical clawed frog npc1 (72% identical), zebrafish npc1 (67% identical), Drosophila melanogaster Npc1a (45% identical), Caenorhabditis elegans ncr-2 (28% identical). Paralogues in human: NPC1L1 (40% identical), PTCH1 (20% identical), PTCH2 (19% identical), PTCHD3 (16% identical), DISP3 (13% identical), DISP1 (13% identical), DISP2 (12% identical), PTCHD1 (12% identical), PTCHD4 (11% identical), SCAP (10% identical).
Diseases named in the same sentence as NPC1 in open-access papers:
NPC1 is named in the same sentence as 240 diseases in open-access papers, as found by Europe PMC text mining. Sharing a sentence is not in itself a finding about the gene and the disease. The quoted sentences say what the papers report.
Niemann-Pick disease type C (199 papers, 2008 to 2026). NPC is a complex lipid storage disease mainly characterized by the accumulation of unesterified cholesterol in the late endosomal/lysosomal compartment. "Two siblings were diagnosed with Niemann‐Pick disease type C due to a homozygous c.145A>T (p.K49*) variant in the NPC1 gene." (PMID 41466769, 2026). "Niemann-Pick disease, type C is an autosomal recessive, fatal, neurodegenerative disorder caused by pathological variants in NPC1 or NPC2." (PMID 41726996, 2026). "Niemann-Pick disease, type C1 (NPC1), is a rare, fatal neurodegenerative disorder caused by pathological variants in NPC1, which encodes a lysosomal cholesterol transporter." (PMID 41912285, 2026). "This was followed by PYGL gene (GSD6, 6 patients/7 variants), NPC1 (Niemann-Pick disease type C1, 5 patients/6 variants) and SLC37A4 (GSD1b/1c, 5 patients/4 variants)." (PMID 41165782, 2025). "Mutations in the NPC1 gene cause a rare, autosomal recessive, neurodegenerative lysosomal storage disorder, namely Niemann–Pick disease type C1." (PMID 41008535, 2025). "We generated models in HEK293T cells of known human pathogenic PTCs corresponding to a TAG stop codon in TPP1, HEXA and NPC1 genes that cause Batten disease, Tay–Sachs disease and Niemann–Pick disease type C1, respectively." (PMID 41261131, 2025). "Among the most compelling findings is the association of a SNP within NPC1 (Niemann-Pick disease, type C1), a gene essential for intracellular cholesterol transport and lipid homeostasis." (PMID 41299637, 2025). "Niemann–Pick disease type C1 and C2 are caused by mutations in the NPC1 and NPC2 gene loci, leading to impaired intracellular cholesterol trafficking and subsequent accumulation of cholesterol and sphingolipids in lysosomes." (PMID 41511290, 2025). "Niemann-Pick type C1 disease is caused by mutations in the NPC1 gene, which encodes a multipass transmembrane glycoprotein required for export of cholesterol from late endosomes and lysosomes." (PMID 39207850, 2024). "Inhibition of NPC1 with its chemical inhibitor U18666A can mimic the loss of function of the NPC1 observed in Niemann-Pick Type C diseases." (PMID 39243069, 2024). "The cysteine-rich luminal loop of the NPC1 protein seems to be a hotspot for genetic mutations associated with Niemann–Pick Disease type C1." (PMID 38397448, 2024). "Niemann-Pick Disease type C is a fatal autosomal recessive lipid storage disorder caused by NPC1 or NPC2 gene mutations and characterized by progressive, disabling neurological deterioration and hepatosplenomegaly." (PMID 38291356, 2024). "Niemann Pick disease type C (NPC) is a lysosomal storage disorder caused by mutations in the cholesterol transport protein NPC1." (PMID 39443481, 2024). "The LSD Niemann-Pick disease type C1 (NPC1) is caused by the loss of function of the lipid transporters NPC1 or NPC2 leading to the accumulation of several GSLs in addition to cholesterol." (PMID 39641585, 2024). "We aim to illustrate the significant benefits of AR cffDNA screening in managing high-risk pregnancies, specifically where biallelic pathogenic variants in NPC1 cause Niemann–Pick disease, type C1 (NPC), a disorder marked by progressive neurodegeneration." (PMID 39161410, 2024). "Niemann-Pick disease Type C (NPC) is caused by mutations in the cholesterol transport protein NPC1 leading to the endolysosomal accumulation of the lipid and to psychiatric alterations." (PMID 39443481, 2024). "Niemann-Pick disease is an autosomal recessive lysosomal lipid storage disorder disease caused by mutations in either Niemann-Pick disease type C1 (NPC1) or the NPC2 gene." (PMID 39416542, 2024). "Niemann–Pick disease type C (NPC) is a fatal neurodegenerative condition caused by genetic mutations of the NPC1 (Chr." (PMID 38254990, 2024).
Niemann-Pick disease type C (continued). "Niemann–Pick type C disease, an autosomal recessive lysosomal storage disorder, is a severe form of impaired cholesterol metabolism caused by a mutation, usually in the NPC-1 gene (Niemann–Pick type C1 gene)." (PMID 39124726, 2024). "Mutations in either NPC1 (95% of cases) or NPC2 (5% of cases) genes cause Niemann-Pick disease type C (NPC), resulting from deficiencies of sphingomyelin phosphodiesterase 1 gene expression." (PMID 39416542, 2024). "In humans, mutations in NPC1 cause Niemann–Pick Type C disease, leading to massive accumulation of cholesterol in lysosomes in all tissues and premature death." (PMID 38696518, 2024). "Niemann–Pick disease type C (NPC) is a distinct subtype of the disease caused by mutations in the NPC1 or NPC2 gene." (PMID 39525762, 2024). "Niemann-Pick Disease type C is divided into type C1 and type C2, which are caused by pathogenic mutations of the NPC1 gene and NPC2 gene, respectively." (PMID 38291356, 2024). "Niemann-Pick disease type C1 (NP-C1) is a rare and devastating recessive inherited lysosomal lipid and cholesterol storage disorder caused by mutations in the NPC1 or NPC2 gene." (PMID 39263569, 2024). "Niemann–Pick disease type C1 (NP-C) (OMIM 257220) results from mutations in the NPC1 gene and is a prematurely lethal genetic lysosomal storage disorder (LSD)." (PMID 37371089, 2023). "Niemann‐Pick disease, type C is a lipid storage disorder caused by the deficiency of one of two proteins, NPC1 (NPC1 gene) or NPC2 (NPC2 gene), although NPC1 mutations are prevalent in the patient population." (PMID 37014126, 2023). "For example, NPC1 mutations are responsible for the vast majority of cases of the neurological disorder Niemann-Pick disease type C, and GWAS studies have shown links between NPC1 and Alzheimer’s disease." (PMID 37792698, 2023). "NPC (Niemann-Pick type C disease) is a lysosomal storage disease where mutations in the NPC1 gene cause the deficiency of the protein, which leads to childhood dementia and death at early/juvenile ages." (PMID 38033125, 2023). "Niemann–Pick disease type C1 (NP-C) is a prematurely lethal genetic lysosomal storage disorder with neurological and visceral pathology resulting from mutations in the NPC1 gene encoding the lysosomal transmembrane protein NPC1." (PMID 37371089, 2023). "Mutations in the NPC1 gene are responsible for Niemann-Pick disease type C1, a lysosomal storage disease that results in intracellular cholesterol accumulation and synucleinopathy lesions." (PMID 37500624, 2023). "Niemann–Pick Disease Type C (NP-C) is an autosomal recessive atypical lysosomal lipid storage disorder caused by mutations of either of two genes: NPC1 (95% of cases) or NPC2." (PMID 37629187, 2023). "Niemann-Pick type C disease is characterized by deficiency of the endolysosomal cholesterol transporter NPC1." (PMID 37407594, 2023). "Acid sphingomyelinase deficiencies encompass types A and B, and Niemann–Pick disease type C includes types C and D. This illness results from deficiencies in either NPC1 or NPC2 transport proteins, leading to lipid storage diseases." (PMID 37629187, 2023). "Among our results, Npc1a and Lip4 are both fly homologs of genes causing the human cholesterol storage disorders, Niemann Pick Disease type C (NPC1) and cholesterol ester storage disease (LIPA)." (PMID 37200393, 2023). "Lysosomal lipid accumulation results in progressive neurodegeneration and neurological impairments in Niemann-Pick type C disease caused by mutations in NPC1." (PMID 38098077, 2023). "The accumulation of cholesterol in lysosomes is reminiscent of the phenotypes in human lysosomal storage diseases, such as Niemann-Pick disease type C (NPC) caused by pathogenic variants in NPC1 or NPC2, which block cholesterol export from the lysosome." (PMID 37736739, 2023).
Niemann-Pick disease type C (continued). "NPC1‐deficient mice recapitulate the neurological condition Niemann‐Pick disease type C. However, crossing to STING‐deficient mice rescues the neuroinflammation and neuropathology observed in NPC1‐deficient mice." (PMID 37139896, 2023). "In Niemann-Pick type C disease, a lysosomal disorder characterized by impaired intracellular cholesterol trafficking, the transmembrane glycoprotein NPC1 misfolds due to disease-causing missense mutations." (PMID 36301667, 2022). "Loss-of-function mutations in NPC1 cause Niemann-Pick type C disease, an autosomal recessive lysosomal disorder characterized by the accumulation of unesterified cholesterol in the endolysosomal compartment." (PMID 36301667, 2022). "Lipids shed by pathogenic mycobacteria have been shown to inhibit NPC1, a lysosomal membrane protein deficient in most cases of a rate inherited lysosomal storage disorder Niemann-Pick disease type C (NPC)." (PMID 36085278, 2022). "NPC1 mutation is responsible for up to 95% of the Niemann-Pick type C disease (OMIM 257220), and it is also a cellular gateway protein for the Ebola virus." (PMID 36262888, 2022). "NPC1 mutation results in a life-limiting lysosomal storage disease, Niemann-Pick disease type C, and increases the risk of hepatocarcinogenesis." (PMID 36572736, 2022). "Previously, we reported that lipids shed by pathogenic mycobacteria inhibit NPC1, the lysosomal membrane protein deficient in the lysosomal storage disorder Niemann-Pick disease type C (NPC)." (PMID 36085278, 2022). "In Niemann-Pick type C disease, the Purkinje cells (PN) located in the cerebellum are the most susceptible to NPC1 loss and are the first cells to degenerate, the greatest loss begins in the anterior part of the cerebellum." (PMID 34596813, 2021). "Niemann–Pick disease type c is another rare, but fatal neurodegenerative disease, which is induced by genetic mutations in NPC1 (I1061T NPC1)." (PMID 33067655, 2021). "Niemann−Pick disease type C (NPC) is a rare neurodegenerative disorder caused by autosomal recessive loss-of-function in either the NPC1 (95% of cases) or NPC2 (5% of cases) genes." (PMID 34377675, 2021). "Niemann–Pick disease type C1 (NPC1) is a fatal congenital neurodegenerative disorder caused by mutations in the NPC1 gene, which is involved in cholesterol transport in lysosomes." (PMID 33256498, 2021). "In the first test case, we examined the protein tree of NPC1, which is a gene that is associated with Niemann–Pick disease Type C, a rare Mendelian disease." (PMID 35068947, 2021). "Niemann–Pick disease type C1 (NP-C1) is a rare lysosomal storage disorder caused by autosomal recessive mutations in the NPC1 gene." (PMID 34830064, 2021). "Deficiencies in either NPC1 or NPC2 cause Niemann–Pick disease type C (NPC), a lysosomal storage disorder characterized by accumulation of cholesterol that is accompanied by increases in other lipids including sphingomyelin and glucosylceramide (GlcCer)." (PMID 33802460, 2021). "Niemann–Pick disease type C (NPC) is an autosomal recessive disorder that develops as a result of NPC1 or NPC2 gene mutation (95% and 5% of patients, respectively) and has been identified as a severe disease associated with lysosomal dysfunction." (PMID 33466390, 2021). "Niemann-Pick type C disease is a rare childhood neurodegenerative disorder predominantly caused by mutations in NPC1, resulting in abnormal late endosomal and lysosomal defects." (PMID 33627648, 2021). "Certain mutations in the NPC1 gene causes Niemann-Pick Type C disease, owing to a defect in the trafficking of endocytosed cholesterol with sequestration of free cholesterol in lysosomes and late endosomes." (PMID 34544283, 2021). "Niemann–Pick disease type C1 (NP-C1) is a neurovisceral disease caused by mutations in the NPC1 gene." (PMID 34830064, 2021).